TSEN2 (tRNA splicing endonuclease subunit 2)
Description:
Constitutes one of the two catalytic subunit of the tRNA-splicing endonuclease complex, a complex responsible for identification and cleavage of the splice sites in pre-tRNA. It cleaves pre-tRNA at the 5'- and 3'-splice sites to release the intron. The products are an intron and two tRNA half-molecules bearing 2',3'-cyclic phosphate and 5'-OH termini. There are no conserved sequences at the splice sites, but the intron is invariably located at the same site in the gene, placing the splice sites an invariant distance from the constant structural features of the tRNA body. Isoform 1 probably carries the active site for 5'-splice site cleavage. The tRNA splicing endonuclease is also involved in mRNA processing via its association with pre-mRNA 3'-end processing factors, establishing a link between pre-tRNA splicing and pre-mRNA 3'-end formation, suggesting that the endonuclease subunits function in multiple RNA-processing events. Isoform 2 is responsible for processing a yet unknown RNA substrate. The complex containing isoform 2 is not able to cleave pre-tRNAs properly, although it retains endonucleolytic activity.
Synonyms: SEN2; SEN2L; MGC2776; PCH2B
Tractability: PROTAC: ubiquitination databases record sites on it.
Gene: Protein-coding gene on chromosome 3 (12,480,529 to 12,541,549, forward strand). Ensembl gene ENSG00000154743.
Subcellular location: Nucleus; Nucleus, nucleolus
Subcellular location (Human Protein Atlas): Nucleoplasm; Centrosome; Cytosol
Pathways (Reactome):
Metabolism of RNA: tRNA processing in the nucleus
Gene Ontology:
Molecular function: protein binding; tRNA-intron lyase activity; nucleic acid binding
Biological process: tRNA splicing, via endonucleolytic cleavage and ligation; tRNA-type intron splice site recognition and cleavage; tRNA processing
Cellular component: nucleoplasm; tRNA-intron endonuclease complex; cytoplasm; nucleolus; nucleus
Genetic constraint (gnomAD): Loss-of-function variants: 50 observed, 52.21 expected, observed/expected ratio (o/e) 0.96, 90% interval 0.76 to 1.21. The upper end of that interval is the gene's LOEUF score, 1.21, which puts it in group 5 of 6, group 1 being the genes least tolerant of losing a copy. Missense variants: 561 observed, 537.52 expected, observed/expected ratio (o/e) 1.04, 90% interval 0.97 to 1.12. Synonymous variants: 177 observed, 187.89 expected, observed/expected ratio (o/e) 0.94, 90% interval 0.83 to 1.07.
Homologues: Orthologues: chimpanzee TSEN2 (99% identical), macaque TSEN2 (86% identical), dog TSEN2 (78% identical), pig TSEN2 (73% identical), rabbit TSEN2 (71% identical), rat Tsen2 (69% identical), mouse Tsen2 (69% identical), zebrafish tsen2 (25% identical), Drosophila melanogaster Tsen2 (14% identical), Caenorhabditis elegans tsen-2 (12% identical).
Diseases named in the same sentence as TSEN2 in open-access papers:
TSEN2 is named in the same sentence as 24 diseases in open-access papers, as found by Europe PMC text mining. Sharing a sentence is not in itself a finding about the gene and the disease. The quoted sentences say what the papers report.
pontocerebellar hypoplasia (3 papers, 2017 to 2025). Pontocerebellar hypoplasias (PCH) are a rare heterogeneous group of diseases characterized by hypoplasia and atrophy and/or early neurodegeneration of the cerebellum and pons. "In a cohort of 169 cases of pontocerebellar hypoplasia, 106 were linked to mutations in four genes (TSEN54, TSEN2, TSEN34 and RARS2)." (PMID 28549128, 2017).
developmental delay (2 papers, 2024). "TSEN2 mutations, although infrequent, result in PCH2B characterized by common neurological findings including microcephaly, developmental delay, intellectual disability, epilepsy, dyskinesia, central visual impairment, and hyperkinetic involuntary movements." (PMID 38622473, 2024).
microcephaly (2 papers, 2024). A congenital or acquired developmental disorder in which the circumference of the head is smaller than normal for the person's age and sex. "A patient with TSEN2 (c.1091C > G) was described by consanguinity, term pregnancy, microcephaly, development delay, intellectual disability, ADHD, and tetraplagia." (PMID 38622473, 2024).
malaria (1 paper, 2010). Malaria is a serious and sometimes fatal disease caused by a parasite that commonly infects a certain type of mosquito which feeds on humans. "Future studies will be needed to define the role of Ppar-γ and Tsen2 in infection and association studies in malaria endemic regions might reveal protective or susceptible polymorphisms in human populations." (PMID 20531941, 2010).
infection (2 papers, 2010 to 2025). The state of being infected such as from the introduction of a foreign agent such as serum, vaccine, antigenic substance or organism. "We confirmed that cells remained viable after knockdown of Tsen2 and Clp1 followed by MHV68-MR infection." (PMID 40444975, 2025). "The tRNA splicing endonuclease, TSEN2, was previously shown to be involved in 5′ pre-tRNA-Tyr production in Clp1K/K mouse embryonic fibroblasts, and so we tested whether the same was true during MHV68 infection." (PMID 40444975, 2025).
infectious disease (1 paper, 2010). A disorder directly resulting from the presence and activity of a microbial, viral, or parasitic agent in humans. "We observed that top functions these genes involved are RNA post-Transcriptional Modification (CLP1 TSEN2 and TSEN54) and infectious disease and inflammatory disease (NR3C1, PPP3CC, and PPP3R1)." (PMID 21172007, 2010).
TSEN2 also shares sentences with these, for which no sentence is quoted: breast carcinoma (1 paper); cancer (1); chronic obstructive pulmonary disease (1); Dyskinesia (1); epilepsy (1); esophageal cancer (1); HIV-1 infection (1); Hypertonia (1); Hypotonia (1); Intellectual disability (1); laryngeal carcinoma (1); oral cancer (1); Paget disease (1); pontocerebellar hypoplasia type 2C (1); prostate carcinoma (1); schizophrenia (1); tumor (1); wart (1).